AMHR2 (anti-Mullerian hormone receptor type 2)
Description:
On ligand binding, forms a receptor complex consisting of two type II and two type I transmembrane serine/threonine kinases. Type II receptors phosphorylate and activate type I receptors which autophosphorylate, then bind and activate SMAD transcriptional regulators. Receptor for anti-Muellerian hormone.
Synonyms: MISRII; MRII; AMHR; MISR2
Tractability: Small molecule: it belongs to a druggable protein family. Antibody: its Gene Ontology location is reachable by antibodies, with high confidence; UniProt predicts a signal peptide or a membrane-spanning region.
Gene: Protein-coding gene on chromosome 12 (53,423,672 to 53,431,672, forward strand). Ensembl gene ENSG00000135409.
Subcellular location: Membrane
Subcellular location (Human Protein Atlas): Vesicles; Cytosol; Nucleoplasm
Pathways (Reactome):
Signal Transduction: Signaling by BMP
Gene Ontology:
Molecular function: anti-Mullerian hormone receptor activity; hormone binding; protein binding; protein homodimerization activity; transforming growth factor beta receptor activity, type II; transforming growth factor beta receptor activity; ATP binding; protein kinase activity; transmembrane receptor protein serine/threonine kinase activity
Biological process: anti-Mullerian hormone receptor signaling pathway; BMP signaling pathway; cellular response to growth factor stimulus; Mullerian duct regression; negative regulation of ovarian follicle development; sex determination; sex differentiation; cell surface receptor protein serine/threonine kinase signaling pathway; female gonad development; male gonad development
Cellular component: plasma membrane; serine/threonine protein kinase complex; receptor complex; membrane
Genetic constraint (gnomAD): Loss-of-function variants: 37 observed, 62.07 expected, observed/expected ratio (o/e) 0.6, 90% interval 0.46 to 0.78. The upper end of that interval is the gene's LOEUF score, 0.78, which puts it in group 3 of 6, group 1 being the genes least tolerant of losing a copy. Missense variants: 638 observed, 736.43 expected, observed/expected ratio (o/e) 0.87, 90% interval 0.81 to 0.93. Synonymous variants: 258 observed, 292.12 expected, observed/expected ratio (o/e) 0.88, 90% interval 0.8 to 0.98.
Homologues: Orthologues: chimpanzee AMHR2 (99% identical), macaque AMHR2 (95% identical), pig AMHR2 (86% identical), rabbit AMHR2 (82% identical), guinea pig AMHR2 (80% identical), mouse Amhr2 (78% identical), rat Amhr2 (77% identical), Drosophila melanogaster wit (28% identical), Drosophila melanogaster babo (23% identical), Drosophila melanogaster tkv (22% identical), Caenorhabditis elegans daf-1 (21% identical), Caenorhabditis elegans sma-6 (18% identical). Paralogues in human: BMPR2 (32% identical), ACVR2A (25% identical), ACVR2B (25% identical), ACVR1B (23% identical), ACVR1C (23% identical), TGFBR1 (23% identical), ACVR1 (23% identical), BMPR1A (22% identical), BMPR1B (22% identical), TGFBR2 (22% identical), ACVRL1 (21% identical).
Diseases named in the same sentence as AMHR2 in open-access papers:
AMHR2 is named in the same sentence as 77 diseases in open-access papers, as found by Europe PMC text mining. Sharing a sentence is not in itself a finding about the gene and the disease. The quoted sentences say what the papers report.
ovarian carcinoma (18 papers, 2010 to 2025). A malignant neoplasm originating from the surface ovarian epithelium. "In the first immunohistochemical study of a large panel of epithelial ovarian cancers and other gynecological cancers, AMHR2 was detected in nearly 70% of epithelial ovarian cancers, as well as in most endometrial cancers and ovarian dysgerminomas." (PMID 39230026, 2024). "AMHR2 is a candidate for therapeutic treatment of epithelial ovarian carcinoma, the most prevalent form of ovarian cancer in the United States." (PMID 39049057, 2024). "Conditional inactivation of multiple genes, such as Pten and Kras or PTEN and Dicer, by expression of Cre recombinase driven by the Amhr2 promoter also led to ovarian cancer in mice." (PMID 24603706, 2014). "The third transgenic model of EOC generated using the Amhr2-Cre transgenic strain was achieved through the conditional inactivation of Dicer and Pten, two genes frequently down-regulated in ovarian cancer." (PMID 23190474, 2012). "Finally, the delayed initiation of ovarian cancer in the FVBB6F1 mice was reflected in a longer mean time to endpoint of 21 weeks compared to 15 weeks observed for the Tg(Amhr2-SV40TAg)1Bcv in the pure FVB/n background." (PMID 23190474, 2012). "Everolimus (a rapamycin derivative) treatment has been shown to reduce tumor growth of cisplastin-resistant clear cell ovarian carcinoma cells and both the onset and progression of ovarian cancer in a mouse model expressing SV40 Large T antigen driven by the MIS type II receptor (Amhr2) promoter." (PMID 21695255, 2011). "In addition, previous reports have shown that AMHR2 expression is common in ovarian cancer cases." (PMID 39230026, 2024). "Thus, the expression of AMHR2 by cancer cells known to be resistant to standard chemotherapy provides a scientific rationale for combination therapy with both 3C23K and chemotherapeutic agents in the treatment of advanced ovarian carcinoma." (PMID 29245952, 2017). "Thus, AMHR2 vaccination may be useful in controlling the more malignant forms of human ovarian cancer." (PMID 26618181, 2015). "Our data derived from both transplantable and autochthonous ovarian tumor models show that vaccination against AMHR2-CD, a defined fragment of an ovarian differentiation protein expressed in the vast majority of human EOCs, provides effective therapy and prophylaxis against ovarian cancer." (PMID 26618181, 2015). "As AMH has been shown to inhibit tumor cell proliferation in several gynecological cancers, including ovarian cancer, through AMHR2‐mediated actions, the AMH‐AMHR2 signaling pathway has emerged as a promising therapeutic target for ovarian cancer." (PMID 39230026, 2024). "The analysis revealed that many of the embryonic and cell development genes are fairly high expressed in ovarian cancer including FOXL2, GATA4, NR5A1, AMHR2, MAL and WIPF3." (PMID 31744494, 2019). "To this end, we and others have shown that anti-Müllerian hormone receptor type II (AMHR2) is expressed in 90% of primary EOCs, 78% of borderline malignancies, 77–86% of non-EOC ovarian tumors, and 56% of malignant ascites from grades III-IV ovarian cancers." (PMID 32499873, 2020).
persistent Müllerian duct syndrome (18 papers, 2012 to 2025). "Our search included terms such as ‘Persistent Müllerian duct syndrome’ + ‘congenital anomalies’, ‘supernumerary testes’, ‘polyorchidism’, ‘genetic testing’, and ‘AMHR2 gene mutations’." (PMID 39682529, 2024). "Where there is a mutation in the AMH gene, or in AMHR2, Persistent Müllerian Duct Syndrome (PMDS) occurs." (PMID 35909548, 2022). "The canonical role of AMHR2 is to inhibit the Müllerian ducts during development of the male fetus, and mutations cause the rare disease persistent Müllerian duct syndrome (PMDS;)." (PMID 22701678, 2012). "Several studies have shown that loss of function, likely pathogenic mutations in either AMH or its receptor anti-Müllerian hormone receptor type II (AMHR2), are associated with the development of persistent Müllerian duct syndrome (PMDS) in humans and other mammals." (PMID 32333774, 2020). "Amhr2-/- males are completely infertile, in agreement with previous reports showing that inactivation of Amhr2 or Amh in humans and mice leads to persistent Müllerian duct syndrome." (PMID 31291191, 2019). "BMP15 was closely related to growth/differentiation factor (GDF) families, BMP families, anti-Müllerian hormone (AMH), and AMH receptor II (AMHR2), which are related to persistent Müllerian duct syndrome, and those proteins were related to the TGF-beta signaling pathway (KEGG)." (PMID 30845640, 2019). "Persistent Mullerian duct syndrome (PMDS) is typified by AMH either not being secreted or being inactive, which occurs as either a result of mutations in the activation of AMH or its receptor, AMHR2." (PMID 39368309, 2024).
Infertility (9 papers, 2013 to 2024). "As previously reported, conditional deletion of Wnt5a with an Amhr2-driver caused infertility and impairment of ovulation." (PMID 32546756, 2020). "On the other hand, polymorphisms in AMH and AMHR2 genes seem to affect hormone biological activities, thus affecting follicle recruitment and development, leading to infertility." (PMID 35761737, 2014). "It is important to discuss the probability (1 in 4) of having another child with PMDS secondary to compound heterozygous AMHR2 gene mutation and the implications of this, including the risks of infertility and malignant testicular or Mullerian derivate transformation." (PMID 39368309, 2024). "Conditional deletion of SMAD1/5/4 exclusively in the cells from mesenchymal lineage (including uterine stroma) using anti-Mullerian hormone type 2 receptor cre (Amhr2-cre) results in infertility with defective decidualization." (PMID 38536963, 2024). "The most common complication of PMDS is infertility, with reports of less than 20 % of patients with AMH or AMHR2 mutations having successfully reproduced." (PMID 39368309, 2024). "In our study, compound heterozygous mutations in exon 9 (c.G1168A (p.E390K)) and exon 10 ((c.A1315G (p.M439V)) of AMHR2 (NM_001164690 transcript) were identified in case 3, who had a history of infertility due to oligospermia." (PMID 35052499, 2022). "Previous study also reported the expression of AMH and AMHR2 mRNA and protein in endometrial glandular epithelium and stromal cells in endometrial tissue obtained during infertility evaluation." (PMID 33263001, 2020). "It is not clear whether specific depletion of Tsc1 in granulosa cells contributes to the fertility/infertility in the Tsc1flox/flox; Amhr2-cre female mice, because of the wide expression of Amhr2-cre in some somatic cells of the reproductive tract." (PMID 23335988, 2013). "Amhr2-Cre is presently the best option for eliciting conditional gene ablation in uterine stroma cells, but the potential confounding effects of ovarian deletion on female fertility must be accounted for to completely characterize subfertility and infertility in subsequent mutant mice." (PMID 38790245, 2024). "Compound heterozygous mutations in c.494_502del (p.I165_A168delinsT) in exon 4 and g.6147C>A of AMHR2 (NM_001164690 transcript) were identified in case 2, who had a history of left laparoscopic hernia repair and bilateral laparoscopic orchiopexy as well as infertility due to azoospermia." (PMID 35052499, 2022).
ovarian tumors (9 papers, 2009 to 2021). "Previous studies have demonstrated that SV40Tag activation with ADCRE or via the Amhr2 promoter can induce ovarian tumours in a relatively efficient manner." (PMID 32645943, 2020). "Generation of constitutively active TGFBR1 in the mouse ovary using Cyp19-Cre reproduced ovarian tumor phenotype, which corroborated findings from studies using Amhr2-Cre." (PMID 27344183, 2016). "In several mouse models of EOC, a single vaccination against AMHR2-CD is sufficient to provide effective immune control over the growth of ovarian tumors." (PMID 26618181, 2015). "The ovarian tumors in Amhr2-Cre;Ctnnb1Δ(ex3)/+;PtenΔ/Δ ovaries showed histopathological features similar to the tumors of Amhr2-Cre;Ctnnb1Δ(ex3)/+ mice." (PMID 21695255, 2011).
endometrial cancer (6 papers, 2013 to 2024). Primary or metastatic malignant neoplasm involving the endometrium (mucous membrane that lines the endometrial cavity). "AMH has been shown to inhibit the growth of human endometrial cancer cell lines with high AMHR2 expression by increasing cell cycle arrest and apoptosis." (PMID 39230026, 2024). "As Amhr2 is not expressed in the epithelial compartment of the uterus, it is reasonable that Pten deletion in the stroma and myometrium could not provoke endometrial cancer." (PMID 33496365, 2021).
endometriosis (4 papers, 2020 to 2025). The growth of functional endometrial tissue in anatomic sites outside the uterine body. "Additionally, AMHR2 expression is observed in the endometrium associated with uterine fibroids, adenomyosis, endometriosis, EC, and other uterine diseases." (PMID 39767233, 2024). "Peritoneal endometriosis expresses AMHR2, the specific receptor for AMH, which may implicate a functional role of AMH in growth maintenance of these lesions." (PMID 33263001, 2020). "The elevated AMHR2 expression in granulosa cells co-cultured with 12Z endometriotic cells suggests that AMHR2, a receptor involved in follicular development signaling, may be upregulated to counterbalance the altered ovarian environment induced by endometriosis." (PMID 40002761, 2025). "AMHR2 is upregulated in the endometrium of women with endometriosis when compared to women without the disease." (PMID 36737777, 2023).
cryptorchidism (3 papers, 2019 to 2022). The failure of one or both testes of a male fetus to descend from the abdomen into the scrotum during the late part of pregnancy. "This raises the question of how many cases with a simple bilateral inguinal cryptorchidism due to AMH/AMHR2 variants may be missed." (PMID 35432193, 2022). "Among the 11 cryptorchidism patients, three had mutations in either AMH or AMHR2, and these three patients were diagnosed with PMDS because pelvic MRI revealed the presence of Müllerian remnants." (PMID 35052499, 2022). "Furthermore, as most PMDS patients were reported to carry genetic variants in AMH or AMHR2 gene, lack of differential diagnosis of cryptorchidism patients will increase the genetic risks in the second generation to a certain extent." (PMID 35052499, 2022).
granulosa cell tumor (3 papers, 2011 to 2023). A slow-growing, malignant tumor, characterize by the presence of granulosa-like cells and Call-Exner bodies, that is almost always found in the ovary. "Our previous study has shown that sustained activation of TGFβ receptor 1 (TGFBR1) driven by anti-Mullerian hormone receptor type 2 (Amhr2)-Cre in the mouse testis induces the formation of testicular granulosa cell tumors (TGCTs)." (PMID 38067144, 2023). "Both females and males harboring Amhr2-Cre mediated overactivation of TGFBR1 develop gonadal tumors reminiscent of granulosa cell tumors revealed by both histological and molecular characterizations." (PMID 38067144, 2023). "We analyzed the expression of inhibin-α and anti-Müllerian hormone (AMH, also known as Müllerian Inhibiting Substance), which are the two markers most often used to detect murine, human, and equine granulosa cell tumors, in Amhr2-Cre;Ctnnb1Δ(ex3)/+ tumors." (PMID 21695255, 2011). "Both the Amh and Amhr2 promoters express in both granulosa cells and OSE, yet their use to express the SV40TAg has led to granulosa cell tumors and epithelial tumors, respectively." (PMID 23190474, 2012). "Interestingly, granulosa cell tumors did not arise in this model, despite the potential for the Amhr2 promoter to drive expression in granulosa cells and the potential for granulosa cells to become malignantly transformed by the SV40 early region or the SV40 large T antigen (TAg)." (PMID 23190474, 2012).
gynecological cancers (3 papers, 2021 to 2024). "In several gynecological cancers, anti‐Müllerian hormone receptor type 2 (AMHR2) mediates AMH‐induced growth inhibition and is expressed at high levels." (PMID 39230026, 2024). "AMHR2 protein expression has been primarily studied in gynecological cancers." (PMID 39230026, 2024).
polycystic ovary syndrome (3 papers, 2013 to 2025). A disorder that manifests as multiple cysts on the ovaries. "AMHR2 mRNA levels in granulosa cells of small follicles have been found to be elevated in cases of polycystic ovary syndrome in humans." (PMID 24265800, 2013). "Some studies show no significant androgen effect on AMH, while others suggest a potential influence in conditions like polycystic ovary syndrome (PCOS) BMPs stimulate AMH and AMHR2 expression, with BMP15, often with GDF9, enhancing AMH expression." (PMID 40410629, 2025).
breast carcinoma (2 papers, 2023). "For ER+ breast cancer patients who have received endocrine therapy, the AMHR2 gene expression levels of the responding group and the non-responding group are similar, and the ROC P-value and Mann–Whitney test P-value both are over 0.05." (PMID 37410375, 2023). "We speculate that the expression of ER and AMHR2 on the surface of breast cancer cells plays a positive role in promoting apoptosis when applying anti-HER2 therapy, and the AMHR2 on the surface of breast cancer cells may be related to chemotherapeutic drug resistance." (PMID 37410375, 2023).
female infertility (2 papers, 2011 to 2013). Diminished or absent ability of a female to achieve conception. "Disruption of Tsc1 introduced by Amhr2-cre caused defects in ovarian folliculogenesis, compromised oocyte/embryo integrity, obstruction of oviduct and failure of implantation, resulting in female infertility." (PMID 23335988, 2013). "In the current study, conditional deletion of Tgfbr1 in the female reproductive tract using Amhr2-Cre expressed in granulosa cells and mesenchymal compartments of the oviduct and uterus led to female sterility." (PMID 22028666, 2011). "It is noteworthy that Amhr2-cre previously used is not only expressed in granulosa cells, but also in the oviduct and uterus, so it is not confirmed whether specific deletion of Tsc1 in granulosa cells results in female infertility or not." (PMID 23335988, 2013).
lung carcinoma (2 papers, 2023 to 2024). "Owing to the lack of NSCLC cell lines expressing high levels of AMHR2, we established a model of AMHR2 overexpression in lung cancer cells using two NSCLC cell lines, A549 and H1299." (PMID 39230026, 2024). "Furthermore, 5%–8% of NSCLCs exhibit high AMHR2 expression, suggesting that AMH may inhibit the progression of some lung cancers." (PMID 39230026, 2024). "However, the clinical relevance of AMHR2 expression and its role in lung cancer is not fully clarified." (PMID 39230026, 2024).
ovarian serous adenocarcinoma (2 papers, 2022 to 2024). An adenocarcinoma that arises from the ovary and is characterized by the presence of malignant epithelial cells that, in well differentiated tumors, resemble the epithelium of the fallopian tube or, in poorly differentiated tumors, show anaplastic features and marked nuclear atypia. "Previously, it was reported that transgenic mice carrying Amhr2-Cre that induced the deletion of DicerloxP/loxP and PtenloxP/loxP alleles in FT stromal cells developed serous ovarian adenocarcinomas." (PMID 35159108, 2022). "Based on these findings, we first optimized the immunostaining conditions of AMHR2 using human ovarian serous adenocarcinoma tissue as a positive control." (PMID 39230026, 2024). "AMHR2 expression was detected mainly in the cytoplasm of tumor cells with a granular pattern in the immunostaining of human ovarian serous adenocarcinoma tissues." (PMID 39230026, 2024).
serous adenocarcinoma (2 papers, 2012 to 2017). An adenocarcinoma that is characterized by the presence of papillary patterns and cellular budding. "In the transgenic mouse model with Dicer and Pten conditionally disabled with Amhr2-Cre, high-grade serous carcinomas arose specifically from the fallopian tube stroma as the earliest lesion, suggesting a mesenchymal origin of HGSC." (PMID 28977852, 2017). "Briefly, while examining the role of KRASG12D and PTEN signaling in granulosa cell development, they noted in triple transgenic mice (Ptenfl/fl;KrasG12D;Amhr2-Cre) that the loss of Pten and gain of KrasG12D in the OSE led to the development of low grade serous adenocarcinomas." (PMID 23190474, 2012).
anovulation (1 paper, 2020). The absence of ovulation. "The identified reproduction-related gene AMHR2 (anti-Mullerian hormone receptor, type II) is a member of protein family AMHR which is a negative regulator of ovulation and dysfunction of it leads to anovulation in humans." (PMID 32904540, 2020).